LOX (lysyl oxidase)
Diseases named in the same sentence as LOX in open-access papers (continued):
Sharing a sentence is not in itself a finding about the gene and the disease.
tumor (continued). "LOX inhibition was associated with increased tumor vascularization, immune cell infiltration, and drug efficacy." (PMID 34356110, 2021). "Recently, collagen cross‐linking and the expression of key enzymes, including lysyl hydroxylase 2 or lysyl oxidase (LOX) and LOX‐like 2 were significantly increased in late‐stage tumours and associated with poor prognosis in patient with OSCC." (PMID 34528373, 2021). "P-selectin-mediated platelet aggregation increases LOX expression, causing tumor ECM remodeling and stiffening, thereby promoting the progression of CRC." (PMID 34502094, 2021). "Research showed that LOX is strongly associated with the establishment and maturation of the tumor microenvironment." (PMID 35047494, 2021). "Fibrosis involves not only upregulation of collagen but also Lysyl oxidase (LOX)-induced cross-linking of collagen fibers further causing tumor stiffening." (PMID 33922795, 2021). "For the liver metastasis of GC, cancer-associated fibroblasts-derived LOX facilitates tumor cell proliferation and outgrowth at the metastatic niche." (PMID 34583752, 2021). "Expression of matrix metalloproteinases (MMPs) 2 and MMP9, as well as lysyl oxidase (LOX) are deemed important contributors to tumor invasion and metastasis, and are linked to the Wnt/β-catenin pathway." (PMID 34638991, 2021). "High LOX levels in the tumor microenvironment causes the cross-linking of extracellular matrix components and increases the stiffness of tumor tissue." (PMID 34572752, 2021). "Another alternative mechanism of tumour stiffness, is mediated by lysyl oxidase which has been implicated in promoting cancer progression and metastasis." (PMID 33048956, 2020). "We observed larger gaps in the ERK5-ko tumors, suggesting that ERK5 depletion resulted in loss of ECM components that are crucial to tumor formation, specifically focusing on factors that cross-link and strengthen the matrix, such as LOX." (PMID 32850332, 2020). "In PTEN-deficient tumor models, enhanced LOX production is responsible for the enhanced attraction of macrophages via the β1 integrin-PYK2 pathway, which subsequently promote tumor growth via SPP1." (PMID 32014107, 2020). "Clinical data suggest that higher expression of LOX enzymes has been found to be associated with invasion, tumor growth, and metastasis in breast, colorectal, and ovarian cancers." (PMID 31540259, 2019). "In Ewing sarcoma, the EWS-FLI oncoprotein downregulates LOX and the reported tumor-suppressive activities have been linked to a propeptide domain." (PMID 31418125, 2019). "LOX enzymes can also remodel the tumor microenvironment and have been implicated in all stages of tumor initiation and progression of many cancer types." (PMID 31130685, 2019). "The tumor stromal region typically consists of excessive amounts of fibrous collagen, which can be cross-linked by soluble mediators, such as lysyl oxidase (LOX), thereby increasing the stiffness of the tumor microenvironment." (PMID 31067787, 2019). "Accordingly, reduced ECM stiffness caused by inhibition of LOX-mediated collagen crosslinking prevents tumor metastasis through effects on cancer cell proliferation and invasion." (PMID 31130685, 2019). "Both tumour cells and surrounding cancer-associated fibroblasts (CAFs) show enhanced expression of the collagen crosslinking catalyst lysyl oxidase (LOX)." (PMID 30406572, 2018). "LOX downregulation has been observed in tumor tissues, and silencing LOX was associated with a more aggressive tumor phenotype and decreased patient survival." (PMID 29732010, 2018). "LOX enzymes presented modulatory effects on activated pericytes, implicated in tumour progression evidenced by an increased migration, proliferation, and angiogenesis in ependymoma and neuroblastoma." (PMID 30406137, 2018).
tumor (continued). "The tumor- and metastasis-promoting function of LOX, in turn, has been linked in many studies to the lysyl oxidase enzyme activity, which is typically increased in cancer cells under hypoxic (low oxygen) conditions." (PMID 30701028, 2018). "Lower LOX level was associated with higher PCa grade and increased risk of tumor-associated mortality." (PMID 29732010, 2018). "In cells that have been transformed by the RAS oncogene or genes signaling through RAS, the tumor suppressive action of LOX has mostly been linked to LOX-PP, which is extracellularly cleaved from pro-LOX and then uptaken by the cells." (PMID 30701028, 2018). "Increased expression of LOX in EOC patient tumor samples associates with poor progression-free survival, linking a putative KDM4B target gene to disease progression." (PMID 27869162, 2017). "The most prominent effects were observed in cultures of tumor-associated pericytes, where the time for reaching the maximum amount of capillary-like structures was longer after inhibition of LOX/LOXL activity." (PMID 28553358, 2017). "Nonetheless, the LOX/LOXL expression profile detected in normal and tumor-associated pericytes differed from the one exhibited by endothelial cells, in which LOX and LOXL2 are the predominantly expressed family members." (PMID 28553358, 2017). "Functional studies revealed that the A-allele decreases the protective capacity of LOX-PP, while increasing the Pro-LOX-associated invasive ability of tumor cells." (PMID 28143503, 2017). "Accordingly, the negatively correlated expression of LOX and miR-141-3p and miR-145-5p is in line with our assumption of decreased tumor suppressive miRNAs and the associated increase of oncogenic targets." (PMID 27336447, 2016). "In conclusion, the results of our study suggest that high LOX expression is associated with tumor progression and a poor prognosis in patients with primary NPC." (PMID 26882568, 2016). "We believe that this is particularly significant because several studies have associated LOX with tumor aggressiveness, and our findings shed light on the mechanism behind this phenotypic observation." (PMID 27296552, 2016). "This miR-200 was then downregulated to increase LOX expression in cancer-associated fibroblast to trigger tumor cell invasion." (PMID 28036074, 2016). "Decreased LOX expression has been observed in a number of cancers and has implicated LOX as a tumor suppressor gene." (PMID 26501565, 2015). "If this was the case, one would predict that LOX inhibition would have a more marginal effect in late-stage disease due to tumours already having significant levels of cross-linked collagen." (PMID 26077591, 2015). "One striking feature of LOX inhibition in the KPC model was stromal alterations that were associated with increased tumor vascularization, immune cell infiltration and drug efficacy." (PMID 26077591, 2015). "Analyses were performed to investigate possible associations between LOX expression in the four different prostate tissue compartments to clinical parameters and histological characteristics of the tumor." (PMID 26501565, 2015). "LOX has been implicated in tumor angiogenesis in vitro and in vivo by increasing vascular endothelial growth factor (VEGF) expression and secretion as well as blood vessel formation." (PMID 25790191, 2015). "High tumor LOX expression is associated with poor distant metastasis-free and overall survival in patients." (PMID 25052686, 2014). "The G473A SNP affects the amino acid sequence of LOX, and the Gln variant encoded by the minor A-allele has been shown to compromise the tumour-suppressive activity of the LOX pro-peptide." (PMID 25141126, 2014). "LOX expression can be both up- and downregulated in cancer and is associated both with tumour suppression and metastasis progression." (PMID 25141126, 2014).
tumor (continued). "The present study analyzed the association between LOX expression and its diagnostic significance for metastasis GC, in condition of combine LOX with serum tumor markers CEA, CA724, CA125, and CA199." (PMID 25060181, 2014). "Immunohistochemical detection revealed that expression of LOX was associated with depth of tumor invasion (P<0.05), lymph node status (P<0.05), TNM stage (P<0.05) and survival (P<0.05)." (PMID 23425977, 2013). "LOX encodes an extracellular copper-requiring enzyme that initiates collagen and elastin crosslinking and enhances tumor cell invasion and metastasis." (PMID 21731642, 2011). "Understanding the molecular mechanisms underlying LOX function could offer novel insights into tumor biology and therapeutic strategies." (PMID 40661776, 2025). "Moreover, expression levels of the LOX gene and the infiltration of M0 macrophages were significantly heightened in the high-risk score group, alongside an increase in tumor mutation burden (TMB)." (PMID 40165301, 2025). "We established a minimal, dual-enzyme metabolic network responsiveto tumor-associated signals, by combining the enzymes LOx and PDC.The cascade functions via sequential signal processing: LOx oxidizeslactate to pyruvate and H2O2, and PDC decarboxylatespyruvate to AcH." (PMID 41387346, 2025). "Lysyl oxidase (LOX) catalyzes collagen crosslinking in the tumor-associated ECM." (PMID 40906383, 2025). "Furthermore, two cell subtypes, LOX+ Fibroblasts and M2 Macrophages, were enriched in tumor tissue and associated with the survival of GC patients." (PMID 39251966, 2024). "Studies have revealed that LOX in ECM may be a pivotal bridge between tumor-associated fibroblasts (CAFs) and tumor cells." (PMID 36293126, 2022). "Interestingly, it is reported that LOX expression is also enhanced in endothelial cells of tumor-associated blood vessels, and that the produced LOX further enhances tumor angiogenesis." (PMID 35682926, 2022). "Nevertheless, they suggest that targeting tumor stiffness with drugs, such as lysyl oxidase inhibitors, may improve treatment access in RAS-mutated CRC." (PMID 35864200, 2022). "LOX, encodes Lysyl oxidase, acts as a tumor suppressor in several cancers, including EwS." (PMID 35740349, 2022). "In addition, the five LOX genes have been linked to fibrosis and cancer when overexpressed, while tumor suppression by the propeptide derived from pro-LOX has been documented." (PMID 35563478, 2022). "In GC, tumor cells in metastatic sites could secrete TGF- β1 to prompt the production of cancer-associated fibroblasts-derived LOX, which may explain the higher fold-change of LOX under the treatment of TGF-β1." (PMID 34583752, 2021). "In addition to the extracellular mechanisms described so far, intracellular LOX is also implicated in tumor progression." (PMID 33669630, 2021). "However, despite the comprehensive research that defines the roles of LOX in tumor progression, a diagnostic platform for the sensitive detection of LOX activity in heterogeneous tumors has not yet been established." (PMID 34572752, 2021). "Notably, higher expression of LOX in the tumor stroma was associated with an advanced clinical stage and poor prognosis." (PMID 34930321, 2021). "Interestingly, they also demonstrated that de novo production of LOX by mesenchymal stromal cells (MSCs) associated to tumor is able to transduce the same signal along the CD44–LOX–Twist axis." (PMID 32793478, 2020). "One mechanism behind this observation appears to be cross-linking of collagen and elastin fibers by enzymes of the lysyl oxidase (LOX) family in the cancer-associated stroma, which provides an enhanced substrate for focal adhesion formation and pro-migratory signaling in tumor cells." (PMID 32064042, 2020).
tumor (continued). "The ascites samples actually do not show an up-regulation of LOX-5-derived products which have been made responsible for tumor-promoting effects of neutrophils, but do show increased levels of LOX and COX-products associated with the resolution of inflammation." (PMID 32098278, 2020). "Uncontrolled tumor cell proliferation and limited tissue blood supply induces intra-tumoral hypoxia, which in turn induces expression of the gene encoding the collagen and elastin cross-linking enzyme lysyl oxidase (LOX) in human tumor cells." (PMID 30356678, 2018). "In summary, our findings reveal a novel involvement of LOX/LOXL family of enzymes in migration and angiogenic properties of both normal and tumor-associated pericytes, supporting the exploration of LOX/LOXL inhibitors to target activation of pericytes within the TME." (PMID 28553358, 2017). "Higher LOX levels were detected in tumor-associated pericytes compared with normal pericytes." (PMID 28553358, 2017). "Here, we performed a comparative characterization of normal and tumor-associated pericytes and report for the first time the modulatory effects of LOX enzymes on activated pericyte properties directly implicated in tumor progression, namely migration, proliferation, and angiogenic activity." (PMID 28553358, 2017). "It is worth noting that, while extracellular LOX is associated with tumor progression, intracellular LOX could be a tumor suppressor." (PMID 27064581, 2016). "We found that LOX staining was associated inversely with tumor stage, approaching significance (p=0.08), in agreement with earlier reports identifying LOX as a tumor suppressor that inhibits Ras." (PMID 26968815, 2016). "In addition we examined if LOX score was associated with other factors detected in tumor and TINT tissue that relate to patient survival." (PMID 26501565, 2015). "LOX expression has been linked to both tumor progression and tumor suppression." (PMID 24265769, 2013). "Interestingly they have shown that inhibiting LOX reverses the increased risk of metastatic tumour formation following chemotherapy, highlighting that a greater understanding of the key mechanisms which drive metastasis hold the potential for treating the disease." (PMID 35713387, 2022). "In addition, the researchers discovered that because of methylation and heterozygozity loss, the tumor suppressor gene of LOX is inactivated in GC and that the expression of LOX may be related to a better prognosis." (PMID 36202905, 2022). "Therefore, the rapid and sensitive detection of LOX in tumor tissue extracts may provide information on whether the tumor is susceptible or resistant to anticancer drugs." (PMID 34572752, 2021). "Moreover, LOX expression in MDA-MB-231 in vivo was positively associated with higher tumor volumes." (PMID 31439905, 2019). "In addition to the role of the LOX in premetastatic niche formation in the lung and collagen crosslinking in the primary tumor, a global quantitative analysis of the hypoxic secretome identified LOX as being significantly associated with bone-tropism and relapse." (PMID 27706047, 2016). "For example, a nanoscale remodeler (SPNcb) that integrates photodynamic therapy with tumor-specific LOX inhibition enables activatable cancer photoimmunotherapy." (PMID 41362727, 2026). "The identification of gene co-expression modules containing classical EMT markers (e.g., VIM, ZEB1, SNAI2) alongside ECM-related genes (COL1A1, FN1, SPARC, LOX) underscores a tightly coordinated interaction driving tumor cell plasticity and invasion." (PMID 40943497, 2025). "Simultaneously, numerous LOX inhibitors have been developed with the goal of serving as potential therapeutic agents for tumour treatment or fibrotic disease management." (PMID 40179101, 2025). "This will enhance comprehension of the mechanisms behind LOX’s involvement in tumor growth and advancement, offering fresh perspectives and possible targets for clinical treatment." (PMID 40661776, 2025).
tumor (continued). "In cancer, LOX can either promote or inhibit tumor development, and its expression level is closely correlated with patient prognosis." (PMID 40661776, 2025). "LOX loss reduces tumor metastasis, while TGF-β and miR-200 enhance LOX expression, influencing matrix remodeling." (PMID 40230452, 2025). "We constructed two models of whole tumor and whole tumor & peritumoral radiomics that can effectively predict the expression levels of LOX." (PMID 40792413, 2025). "Specifically, the family of LOX can generate an immunosuppressive microenvironment within a tumor by promoting the polarization of M2 macrophages and suppressing the activity of CD8+ T cells." (PMID 40270974, 2025). "TAMs, CAFs, and tumor cells secrete proteolytic enzymes — including metalloproteinases, cathepsins, and lysyl oxidases (LOX) — that reorganize ECM components." (PMID 40662361, 2025). "TM also inhibits copper-dependent enzymes, such as superoxide dismutase (SOD1) and lysyl oxidase (LOX), which play crucial roles in regulating oxidative stress and remodeling the extracellular matrix—key processes in tumor development and metastasis." (PMID 40406488, 2025). "Immunofluorescent staining revealed increased infiltration and exhaustion of CD8+ T cells in the tumor tissues of mice in the sh-LOX, sh-LOXL1, sh-LOXL2, sh-LOXL3, and sh-LOXL4 groups, compared to the sh-NC group." (PMID 40270974, 2025). "It is important to acknowledge the potential for a correlation between the selected imaging features and tumor progression, tumor microenvironment, or LOX expression." (PMID 40792413, 2025). "Different genetic settings for P4HA1, MT1-MMP and LOX were tested to assess their impact on the tumour growth." (PMID 39751947, 2025). "Among the upregulated proteins in the LLN group, LOX (lysyl oxidase enzymes), which catalyze the crosslinking of collagens and elastin, increasing the tissue stiffness, has been proven to promote tumor progression through increased integrin signaling and EMT." (PMID 40075679, 2025). "Flow cytometry analysis revealed a significant reduction in the proportion of M2 macrophages in the tumor tissues of sh-LOX, sh-LOXL1, sh-LOXL2, sh-LOXL3, and sh-LOXL4 groups of mice compared to the sh-NC group." (PMID 40270974, 2025). "Proteolytic enzymes, like LOX carried by tumor-derived EVs, cross-link collagen fibers in these niches, resulting in a stiffened matrix that facilitates the adhesion of circulating tumor cells." (PMID 40149289, 2025). "Combination therapies based on the copper chelator TM (e.g., synergistic LOX/TGF-β inhibitors) have the potential to reduce tumour resistance to copper depletion by effectively overcoming adaptive resistance." (PMID 40809021, 2025). "Our findings suggest that the increased HIF-1α, LOX and ITGA5 expression in the tumor microenvironment is associated with decreased PFS, potentially reflecting resistance to treatment." (PMID 39857068, 2025). "The radiomic model of the whole‐tumor and peri‐tumor region also has a good predicting effect in the expression of LOX." (PMID 40792413, 2025). "Inhibition of LOX can weaken the fibrillar collagen network and improve the pathway of T cells into the tumor." (PMID 40211368, 2025). "Paradoxically, tumour cells increase the tissue stiffness (e.g. LOX), which is believed to physically restrict invadopodia extensions, impeding cell movement." (PMID 39917412, 2025). "LOX plays a significant role in tumour metastasis through the production of hydrogen peroxide (H2O2), which activates Src/FAK signaling and the EMT process." (PMID 40809021, 2025). "Previous work indicated that the lysyl oxidase (LOX) score in TINT epithelium was correlated with tumor stage and PC survival." (PMID 40260402, 2025). "It has also been shown in mouse mammary carcinoma cells that downregulation of ATP7A led to the loss of LOX-mediated phosphorylation of focal adhesion kinase 1 (FAK1), a key regulator of tumor cell adhesion and motility." (PMID 40721800, 2025).